COL4A1 (collagen type IV alpha 1 chain)
Diseases named in the same sentence as COL4A1 in open-access papers (continued):
Sharing a sentence is not in itself a finding about the gene and the disease.
tumor (continued). "Thus, COL4A1 and COL13A1 production in cancer cells supports their high invasion capability into the bladder wall and promotes subsequent tumor progression and metastasis in orthotopic bladders." (PMID 28415608, 2017). "FR exhibited a high level of basement membrane proteins and fibroblast lineage markers (COL4A1, FBLN5, DCN, DPT) and is enriched for ECM organization, wound-healing, and cell adhension pathways, suggesting a potential shared mechanism between tumor-surrounding stroma and tissue repair." (PMID 39870619, 2025). "Additionally, genes like COL4A1, PLOD2, and PXDN, which participate in extracellular matrix remodeling, alongside immune-related genes such as CYFIP2, EMP3, and HLA-B, are instrumental in modulating the tumor microenvironment and facilitating immune evasion." (PMID 39949776, 2025). "Interestingly, ITGAV expression did not significantly differ between tumor cells in the stroma FOV (FDR = 0.934) while COL4A1 shows a slightly higher expression following IO exposure compared to IO naïve FOV (FDR = 0.023)." (PMID 39639369, 2024). "A visual check of the spatial distribution for three of the niche-DE genes (COLGALT1, COL4A1, and CTBP2), each in a separate patient sample, reveals that niche-DE gene expression are indeed enriched in regions of the tissue where fibroblasts and tumor cells colocalize." (PMID 38217002, 2024). "Another matrix CAF subcluster, C11, was linked to angiogenesis and highly expressed NOTCH3 (an important receptor in vascularization and angiogenesis), COL18A1 (involved in angiogenesis regulation), COL4A1, and COL4A2, which might promote the proliferation and metastasis of tumor." (PMID 38010945, 2024). "For example, gene expression levels of COL1A1, COL6A3, and FN1 in CAFs as well as COL4A1 and COL4A2 in Angiogenic_EC were correlated with the proportion of the Cancer_Malig subtype in BC and CRC, indicating these pEMT tumor cells might be regulated by COL1A1 in CAFs and COL4A1 in Angiogenic_EC." (PMID 38002057, 2023). "Consequently, we hypothesized that lnc-TRIM28-14, CD93 and COL4A1 could regulate GCPM and could be novel tumor markers and potential therapeutic targets for GCPM." (PMID 36690975, 2023). "Therefore, our finding showing a positive correlation between COL4A1 expression levels and TEC signatures suggests that COL4A1 may be involved in angiogenesis, which is a critical step in tumor progression." (PMID 35455650, 2022). "Substantial differences between tumor and neighboring healthy cortex were found in both interstitial matrix proteins, such as collagen 6 (COL6A1, COL6A2, COL6A3), and basement membrane components such as collagen 4 (COL4A1, COL4A2) and laminins (LAMA5, LAMA4, LAMB1, LAMB2, LAMC1)." (PMID 34884982, 2021). "COL4A1 and COL13A1 expression was notably increased in the trabecular and infiltrative patterns compared with that in the nodular pattern (P = 0.017 and 0.012, respectively), implying that the expression of these two collagens increases biological aggressiveness and tumor invasiveness in human UCB." (PMID 28415608, 2017). "Interestingly, COL4A1 expression levels were significantly upregulated in most cancer types in RNA-sequencing-based TCGA datasets and the integrated microarray-based cancer-expression database GENT, implying the potential correlation of COL4A1 expression with tumorigenesis or tumor progression." (PMID 35455650, 2022). "Moreover, it is reported that COL4A1 protein is mainly distributed in the stromal region around the cancer cell site, which can degrade E-cadherin and other adhesion molecules through the AKT signaling pathway to trigger tumor sprouting and promote tumor invasion." (PMID 32637572, 2020). "Considering the mutant phenotypes of both COL4A1 and COL4A2 included metabolism phenotype and the GO annotations related to them contained extracellular matrix structural constituent, the two metabolism-related genes may be released by tumor cells and mainly play a role in cancer stroma." (PMID 32704448, 2020).
tumor (continued). "On the other hand, Col4a1, Col4a3, Col4a5, Col5a3, Col11a2, Col14a1, Col15a1, Col16a1, and Col22a1 were found in normal ECM but not in tumor ECM; Col25a1 was found only in tumor ECM but not in normal ECM." (PMID 36547361, 2022). "Results demonstrate that tumor scaffold, in the absence of LKB1 overexpression, repressed COL1A2 and IGFBP4, and enhanced COL4A1 compared to MDA-MB-231 cells grown on TCP." (PMID 35755802, 2022).
cancer (86 papers, 2009 to 2025). A tumor composed of atypical neoplastic, often pleomorphic cells that invade other tissues. "Machine learning identified five potential diagnostic biomarkers (COLEC12, TMCC1, CEP55, KLK3, COL4A1) with an AUC of 0.903, which are implicated in immune modulation and cancer progression." (PMID 40427030, 2025). "Previously, other studies proposed COL1A1, COL1A2, and COL4A1 as candidate diagnostic markers for this cancer." (PMID 38041130, 2023). "Many of the ECM components that showed differential expression and were highlighted in the hypernetwork analysis, including MMPs, TIMP3, FN1, LAMC1, and COL4A1/6A2, have previously been reported as prognostic or diagnostic markers in different cancers." (PMID 35267606, 2022). "From among these 22 networks, we identified only one network containing COL4A1, which was associated with connective tissue disorders, organismal injury and abnormalities, and cancer (top)." (PMID 28415608, 2017). "However, COL4A1 was predominantly expressed in stromal cells, including cancer-associated fibroblasts (CAFs) and endothelial cells." (PMID 40351420, 2025). "For example, the stromal subset consisted of endothelial cells identified by expressions of VWF, PECAM1 and KDR, pericytes with high RGS5, ACTA2, and COL4A1 expressions, and cancer-associated fibroblasts (CAFs) identified by significant expressions of COL1A1, DCN and LUM." (PMID 38925650, 2024). "Both of these subtypes shared characteristics of myofibroblast cancer-associated fibroblasts (mCAFs) because of the high level of expression of the genes encoding extracellular matrix building, i.e., COL4A1; ECM remodeling proteins, i.e., MMP11; and contractile proteins, i.e., TPPP3 and MYL9." (PMID 39796089, 2024). "However, COL4A1 was mostly expressed in adjacent stromal cells, such as cancer-associated fibroblasts (CAFs) and endothelial cells." (PMID 35455650, 2022). "Moreover aberrant DNA methylation pattern of COL4A1 gene in the gene body was associated with cancer." (PMID 29859035, 2018). "The highest expression of genes encoding Col1a1-2, Col3a1, Col4a1, Col4a2, Col5a1, Col5a2, Col6a1, Col8a1, Col9a3, Col10a1, Col12a1, Col14a1, Col15a1, Col16a1, Col18a1, and Col28a1 were detected in untreated tumors, whose landscapes were dominated by Krt8+ cancer cells." (PMID 39372930, 2024). "For COL4A1, inhibitors of integrin signaling, which play a critical role in the interaction between collagen and cell receptors, have shown promise in other cancers." (PMID 40087784, 2025). "Using the PanCan Atlas from TCGA, expression of ITGAV and COL4A1 transcripts was found to be the highest in ccRCC specifically, compared to all other cancers." (PMID 39639369, 2024). "Studies have shown that genes such as COL4A1 are involved in cancer development and metastasis, suggesting the complex interplay between gene expression and cancer dynamics." (PMID 39529627, 2024). "Among them, abnormal expression of COL4A1 and COL4A2 disrupts the strict regulation of the ECM and promotes the proliferation and invasion of cancer cells, which is often the main cause of cancer metastasis, recurrence and even death." (PMID 38016970, 2023). "In comparison to normal tissues, Nos2, Hgf, Lama1, Csf3r, Csf2rb2, Col4a1, Col4a2, Adcy2, Adcy4, Gstm3 and Gstm6 were identified as the most significant genes in cancer pathways." (PMID 37774039, 2023). "For example, COL4A1 overexpression plays a pivotal role in the carcinogenesis and metastasis of various cancers." (PMID 35455650, 2022). "Expression of COL4A2 is highly correlated with that of COL4A1 in all types of cancers in TIMER2 analysis and exclusively expressed in stromal cells like COL4A1 in single-cell sequencing data (data not shown)." (PMID 35455650, 2022).
cancer (continued). "The extended analysis of top seven collagen genes among 11 cancer types shows a consistent positive correlation between the fractions of endothelial cells and expression of basement membrane (COL4A1 and COL4A2) and multiplexin (COL15A1) collagen subfamily." (PMID 36321857, 2022). "Collectively, the data from the two analyses showed that COL4A1 expression was upregulated in most cancer types." (PMID 35455650, 2022). "Downregulation of COL4A1 gene expression can lead to a significant reduction of the S-phase cell ratio in cancer cell cycle and arrested in the G0/G1 phase." (PMID 32637572, 2020). "Previous studies have shown that COL4A1 is essential in tumorigenesis, which contributes to the proliferation, migration and colony formation in many cancers." (PMID 32704448, 2020). "As FAK has been reported to affect Src and AKT activation in cancer, it is convincing that COL4A1 is involved in the proliferation and migration of HCC cells through FAK-Src signaling as type IV collagen molecules." (PMID 32746865, 2020). "COL4A1 was also identified as the potential therapeutic target genes in several human cancers including CRC." (PMID 31736743, 2019). "High MMP9 mRNA expression levels were associated with the expression of genes involved in cancer progression: BRCA2, COL4A1 and ITGA6, and were also associated with high FABP4 mRNA expression levels." (PMID 31874999, 2019). "In luminal B HER2- cancers, only high COL4A1 expression significantly impacted OS." (PMID 39850811, 2024). "Notably, COL4A1 exhibited the highest mean rank scores across cancers, with increased expression observed in almost all cancers." (PMID 39345334, 2024). "Besides VIM, the basement membrane also promotes cancer cell invasion and metastasis, COL4A1 and COL4A2 are typical basement membranes ubiquitously expressed on cells." (PMID 37642765, 2023). "Notably, macrophage signatures among the examined immune cell types displayed the highest correlation with COL4A1 expression in all four cancer types." (PMID 35455650, 2022). "To identify the cancer types in which increased expression of COL4A1 was correlated with patient survival, we performed a Kaplan–Meier survival analysis of two patient groups split by optimal cut-off to maximize survival differences in TCGA datasets depending on the expression levels of COL4A1." (PMID 35455650, 2022). "It is possible that overexpression of RUNX1 in these cancer types could also activate COL4A1 expression to promote tumorigenesis." (PMID 32746865, 2020). "Some studies have reported that mRNA levels of COL4A1 are also subject to posttranscriptional control such as microRNAs, suggesting that the expression of COL4A1 in cancer may be regulated by multiple mechanisms." (PMID 32746865, 2020). "Similarly, COL4A1 interactions with SDC1 (CD138) on malignant plasma cells may facilitate cancer cell adhesion and survival." (PMID 39596117, 2024). "Previous work has shown that COL4A1 contributes to ECM remodeling and invasive behaviour in multiple cancer types." (PMID 41291892, 2025). "Previous studies revealed that COL4A1 promotes EMT, a critical step in cancer metastasis, by modulating signaling pathways such as TGF-β and PI3K/AKT." (PMID 40087784, 2025). "In this study, treatment with Metformin was more effective than Pirfenidone or MitoQ in reducing both the levels of COL4A1 and COL1A1 as well as preventing a shift to glycolysis, typically occurring in cancer cells and pro-fibrotic myofibroblasts." (PMID 40104066, 2025). "Key genes such as COL1A1, COL4A1, PIK3CA, PIK3R1, and mTOR were found to be overexpressed, correlating with increased cancer aggressiveness." (PMID 39850811, 2024).
cancer (continued). "Of note, COL4A1 and HLA-G were screened as hub ligands in the TAM-cancer stem cell (CSC) interactions." (PMID 33971970, 2021). "A comparison of genome-wide methylation profiles of NHK and cSCC cell lines revealed a statistically significant difference in methylation in 361 unique genes (adjusted p-value ≤ 0.01), including known cancer drivers (MAP2K2, WNT5A, COL4A1, BMP2 and FGF7)." (PMID 31336867, 2019). "Among these genes, collagen 3A1 (COL3A1), collagen 4A1 (COL4A1), collagen 4A2 (COL4A2), and laminin 5 were upregulated in the majority of cancer lesions." (PMID 29720137, 2018). "In this regard, we suggest that the vicinity of cancer cells can induce normal fibroblasts to become “active fibroblasts”, which produce higher levels of specific markers, including TIMP3 and COL4A1." (PMID 24039846, 2013). "The biological relevance of the aberrantly methylated and expressed genes was cancer process, including IRS1 that is related to transformation, and collagen-related genes such as COL4A1, COL4A2 and COL6A3." (PMID 23818951, 2013). "The two other genes in our OSCC recurrence signature (COL4A1 and MMP1) are better characterized in cancer." (PMID 21989116, 2011). "In addition, this panel includes ECM components that stimulate cancer cell invasion, such as collagens (e.g., COL1A1, COL4A1), the extracellular matrix glycoproteins laminins (e.g., LAMA1, LAMC1), fibronectin (FN1), and SPARC, among others." (PMID 38437557, 2024). "In addition, ERFE was co-expressed with the genes involved in extracellular matrix (ECM) deposition and remodeling, including PXDN, COL4A1, and LOXL2 that are known to promote cancer invasion and metastasis." (PMID 36675239, 2023). "Genes positively correlated with purity showed enrichment in cancer-related pathways and processes such as epithelial-mesenchymal transition (BASP1, COL4A1, THBS2), genes involved in the TNFA signaling via NFKB (SPSB1, SMAD3), and genes upregulated by KRAS activation (CFB, MAFB)." (PMID 37041233, 2023). "Therefore, this study indicates the potential relationship between COL4A1, which is overexpressed in the TME, and cancer immunity." (PMID 35455650, 2022). "Therefore, our database-based pan-cancer analysis suggests that these four collagen family genes (COL5A1, COL3A1, COL4A1, and COL15A1) have commonality with the progression of various tumors." (PMID 34691289, 2021). "COL4A1, a subunit of type XIII collagen, is a crucial gene for cancer cell migration and invasion." (PMID 33971970, 2021). "Among other highly expressed genes in SPFs without CCCM stimulation, we found POSN, SPARC, or COL4A1, which are known to be highly expressed in the cancer stroma; and many of these are prognostic factors." (PMID 24505356, 2014). "In addition, COL4A1 could activate FAK-Src signaling pathway and then facilitate cancer progression and metastasis." (PMID 39741182, 2025). "At the same time, multiple collagen-related genes (COL6A2, COL3A1, COL4A1, and COL4A2) in the MSC-2 cluster were upregulated in bone metastases, which is consistent with our observation of IGFBP3, TAGLN, LUM, COL6A1, COL6A2, and COL3A1 in pan-cancer in Fig. (1d)." (PMID 39156727, 2024). "In cancer, combined over-expression of COL4A1 and LAMC2 can distinguish OSCC from clinically normal oral cavity/oropharynx tissues; this latter study suggests that COL4A1 over-expression may be a useful biomarker for early detection of malignancy." (PMID 21989116, 2011). "Unlike the other three cancer types, the survival rates of the LGG patient group with low COL4A1 expression declined significantly from approximately 150 months, eventually disappearing after approximately 170 months." (PMID 35455650, 2022). "Numerous studies have proved that FABP4, COL4A1, and RGS4 were related to various types of cancer progression; however, we searched GIST on PubMed with no reports on our screened differential genes and GIST." (PMID 35646090, 2022).
cancer (continued). "No up-regulated genes, but four down-regulated genes (COL4A1, COL4A2, EPAS1 and FGF15) of the "Pathways in cancer" were found in both cell lines." (PMID 25992885, 2015). "XAGE-1, COL4A1, S100P and TM4SF1 were observed to show elevated expression in various cancers, but the expression level of these genes in HCC has not been reported previously." (PMID 19171046, 2009). "Furthermore, COL4A1 and ITGA5 are not specific to GC, and studying these hub genes can therefore increase the understanding of other cancers." (PMID 30002985, 2018). "Interestingly, recent studies show that cleavage products derived from the non-collagenous domain of both COL4A1 and COL4A2, have significant anti-angiogenic effects on endothelial cells including increased apoptosis and decreased proliferation, and are being explored as novel cancer therapeutics." (PMID 26010865, 2015).